PALB2 (partner and localizer of BRCA2)
Diseases named in the same sentence as PALB2 in open-access papers (continued):
Sharing a sentence is not in itself a finding about the gene and the disease.
cancer (continued). "We performed targeted sequencing analyses of all coding exons of BRCA1, BRCA2, and PALB2, as well as sequencing mutational hotspots of 50 cancer-associated genes in the 42 PDAC tumors with paired normal tissues using a next-generation sequencing platform." (PMID 29802286, 2018). "The level of cancer risk associated to PALB2 pathogenic variants is known to be low in comparison to BRCA2 pathogenic variants, but enough to propose a clinical management of the familly contrary to other low risk genes, notably CHEK2 1100delC and ATM." (PMID 29707112, 2018). "Among all described carriers of bi-allelic PALB2/FANCN mutations who developed cancer in early childhood, four had WT." (PMID 30344923, 2018). "From the role in DNA damage repair to the impact of gene mutations in cancer predisposition, passing through PALB2 molecular features and interaction partners depicting its role as a tumor suppressor gene." (PMID 28858227, 2017). "In the cancer patient group, the recurrent variants (c.172_175delTTGT and c.509_510delGA) accounted for 86% (6/7) of PALB2 mutations." (PMID 28279176, 2017). "We also examine the involvement of PALB2 mutations in the predisposition to cancer and the role of PALB2 in stimulating error-free DNA repair through the FA/HR pathway." (PMID 28858227, 2017). "We demonstrate that two cancer-associated missense mutations in the ChAM of PALB2 hinder its chromatin association." (PMID 29387807, 2017). "As part of our on-going efforts to characterise the function and regulation of PALB2 chromatin association, we investigate the link between perturbations of PALB2 chromatin association and cancer." (PMID 29387807, 2017). "The family history of these patients included BC/OC and other types of cancer, as shown in the pedigrees of 2 patients with PALB2 and TSC2 mutations." (PMID 28423363, 2017). "Functional characterization of cancer-causing mutations in PALB2 suggested that the C-terminal region containing four WD40 motifs binds to BRCA2." (PMID 27490902, 2016). "The PALB2 interest group continues work to further refine breast and other cancer risks for PALB2 mutation carriers." (PMID 27099641, 2016). "Biallelic loss of PALB2 causes increased predisposition to cancers, increased sensitivity to DNA-damaging agents, and Fanconi anemia." (PMID 25636233, 2015). "Germline PALB2 mutations are rare, but have been associated with increased risk for breast and other cancers." (PMID 25636233, 2015). "Carriers were affected by bi-allelic mutation in PALB2 that led to the onset of early childhood cancers, along with other FA disease traits including growth retardation and congenital malformation." (PMID 24949998, 2014). "Because PALB2 germline truncating mutations are relatively rare, the full spectrum of cancer predisposition associated with these mutations has yet to be fully characterized." (PMID 24949998, 2014). "Germline PALB2 mutations are rare, but have been reportedly associated with increased predisposition to breast and other cancers." (PMID 23977390, 2013). "Our findings, taken together with previous reports, support adding PALB2 c.2323C>T p.Q775X to the list of cancer susceptibility genes for which founder mutations have been identified in the French Canadian population." (PMID 23302520, 2013). "The families of several probands identified in this study as carriers of frameshift or nonsense mutations of PALB2 were observed to include numerous diagnoses of other cancers." (PMID 23448497, 2013). "Biallelic loss of PALB2 causes increased predisposition to cancers, increased sensitivity to DNA damaging agents and Fanconi’s Anemia." (PMID 23977390, 2013). "The identification of yet additional families with this as well as other PALB2 mutations will lead to better estimates of the associated cancer risks and to better understanding of the optimal surveillance and prophylactic regimens for mutation carriers." (PMID 23941127, 2013).
cancer (continued). "Family cancer histories of probands, carriers of PALB2 mutations, and the histopathology features of PALB2-associated tumours." (PMID 23448497, 2013). "The possible implication of PALB2 as a predisposition gene in other cancers would need to be further investigated." (PMID 23448497, 2013). "The cancer types of the three observed PALB2 mutation positive individuals fitted well to that described previously: all three cases had ductal tumor histology and exhibited positive estrogen and progesterone receptor status." (PMID 23941127, 2013). "Heterozygous mutations in PALB2 have been linked to a higher risk of breast and pancreatic cancer, while homozygous mutations cause Fanconi anemia, a rare genetic disorder characterized by genomic instability and increased cancer risk." (PMID 39941813, 2025). "PALB2 germline mutations are inherited in an autosomal dominant manner, and, when a pathogenic mutation is found in first-degree relatives, cascade testing is advised for determining the cancer risk." (PMID 41374970, 2025). "Heterozygous germline variants in PALB2 significantly increase the risk for various cancers, including breast, ovarian, pancreatic, prostate, colorectal cancer, and so forth, with a significant decrease in these patients’ survival." (PMID 40040726, 2025). "Notably, a deeper understanding of PARPi has revealed that in addition to its efficacy against conventional tumors with BRCA pathogenic variants, cancer patients with PALB2 pathogenic variants also appear to derive benefit from this therapy." (PMID 40822464, 2025). "Therefore, it is understood that the genes BRCA1, BRCA2, and PALB2 are key cancer susceptibility genes." (PMID 40869938, 2025). "Similarly, CX5461 has been used for early-stage clinical studies of BRCA1-, BRCA2-, and PALB2-mutated cancers." (PMID 41203590, 2025). "The variant may influence PALB2 function, therefore exacerbating DNA repair and changing the potential cancer risk after the exposure to cytostatic drugs." (PMID 40040726, 2025). "Further understanding of these mechanisms may eventually pave the way for improved personalized cancer therapy of PALB2 mutation carriers, and possibly also to carriers of functionally related cancer susceptibility gene defects in e.g., BRCA1 and BRCA2." (PMID 38597967, 2024). "This suggests that PALB2 and BRCA2 may be associated to similar carcinoma risks because BRCA2 needs PALB2 to be recruited in the HR repair." (PMID 38672070, 2024). "The implications of these data are that cancers with PALB2 and BRCA2 inactivating mutations may be the optimal group for Polθi monotherapy." (PMID 38001070, 2023). "The dissection of specific protein functions within HR revealed that Polθi monotherapy may provide greater benefit for cancers with PALB2 and BRCA2 mutations relative to those with BRCA1 mutations." (PMID 38001070, 2023). "A recent trial of the mTOR inhibitor, everolimus, in combination with cisplatin given preoperatively to TNBC patients with residual disease following preoperative anthracycline/taxane showed responses to therapy in patients whose cancers had a PIK3CA mutation or a germline PALB2 mutation." (PMID 37491309, 2023). "If these variants are germline, ARID1A might be a better indicator of cancer risk than PALB2 in the Mexican-mestizo populations." (PMID 37182128, 2023). "The next step was to verify the presence of additional pathogenic and clinically relevant variants in CHEK2 and PALB2 genes that may be associated with increased cancer risk in the analyzed samples." (PMID 35456488, 2022).
cancer (continued). "Biallelic mutations in PALB2 cause Fanconi anaemia (FA), a rare genetic disorder characterised by bone marrow failure, developmental abnormalities, and an increased incidence of childhood cancers." (PMID 36269050, 2022). "Additionally, PALB2 showed high expression in various cancers and was associated with a poor prognosis." (PMID 36158641, 2022). "Altogether, we identify two novel PALB2 VUSs, p.L24F and p.L35F, that compromise PALB2 function and may increase cancer risk." (PMID 35853885, 2022). "In addition, a germline truncating PALB2 variant was also found meaning that two cancer predisposition gene variants with implications for genetic counselling were present in the same individual." (PMID 33854214, 2021). "Biallelic mutations in PALB2 result in a subtype of Fanconi anemia, which is a rare autosomal recessive syndrome characterized by genome instability, early bone marrow failure, growth abnormalities and increased cancer susceptibility." (PMID 33718150, 2021). "Over the past years, several studies have shown that germline loss-of-function variants in the PALB2 gene may confer an increased lifetime risk of breast, pancreatic, ovarian and other cancers." (PMID 33718150, 2021). "Our results will help to further delineate a complex mechanism of PALB2 function in chromatin maintenance, to better predict pathogenesis of known and newly identified mutations and to advance personalized treatment of cancer in patients with different genetic backgrounds." (PMID 34946951, 2021). "To assess the pathogenicity of the variant further, we correlated mutational frequencies of each PALB2 nucleotide by comparing its germline variation in healthy individuals (Gnom‐AD v2.1.1 non‐cancer n = 118.479) and somatic mutations in cancer (COSMIC v91 n = 37,221)." (PMID 34382369, 2021). "Our analyses of sensitivity of PALB2 deficient cancer cells to inhibition of the different DNA repair pathways also offer a valuable data resource for testing and building new hypothesis on." (PMID 34084283, 2021). "Thus, this study unveiled a unique function of PALB2 during oxidative stress and provided a possible link between the oxidative stress response and PALB2-associated cancer formation." (PMID 32185139, 2020). "In addition, our study evaluated a more extensive (n = 94) set of cancer predisposition genes, and detected mutations in genes such as PALB2, which has been associated with heritable forms of TNBC." (PMID 33302456, 2020). "Importantly, the cancer spectrum caused by mutations in PALB2 is quite similar to that induced by mutations in BRCA2, thereby validating the direct interaction between PALB2 and BRCA2." (PMID 32300589, 2020). "We also included ATM and PALB2 for research purposes, excluding them from the clinical report, under the assumption that their variants could play a role in families with known cancer associations, that is, CM and PC." (PMID 32325837, 2020). "We identify inactivation of BRCA1, BRCA2, RAD51C, and PALB2 as the most frequent genetic cause of HRD pan-cancer in both primary and metastatic cancer, with the latter two genes resulting in the same mutational footprints as BRCA2 (consistent with the findings of recent studies in breast cancer)." (PMID 33149131, 2020). "BRCA1, BRCA2, PALB2 variants are also associated with increased risk of ovarian and other cancers." (PMID 35582724, 2019). "Thus, we report on the development of a relatively rapid and easy functional assay that can determine the functional consequences of VUS in PALB2, thereby facilitating cancer risk assessment and predicting therapy response." (PMID 31757951, 2019). "This new role for PALB2 could lead to the discovery of other DNA repair mechanisms, and could be used to predict which PALB2 mutations are more likely to cause cancer." (PMID 31017574, 2019).
cancer (continued). "Interestingly, genomic profiling of our patient’s cancer identified a mutation in PALB2, a gene intimately involved in DNA repair machinery, suggesting a potential genetic basis for immunotherapy response." (PMID 29743117, 2018). "Additionally, combining findings from this study with data from previously published studies allowed a more complete analysis of the role of the cancer predisposition genes PALB2 and BRCA2." (PMID 29706558, 2018). "PALB2 cancer association studies were mainly focused on truncating mutations, but the presence of missense variants of unknown significance (VUS) has also been reported in patients." (PMID 28858227, 2017). "Although further clinical evidence is required, our observations suggest that PALB2 S417Y may be a low-penetrance genetic variant associated with low cancer risk or a neutral variant." (PMID 29387807, 2017). "Given the emerging evidence that missense substitutions in protein-binding domains of PALB2 are connected with disease predisposition, we aimed to elucidate whether cancer-associated missense mutations may also perturb the function of the PALB2 ChAM." (PMID 29387807, 2017). "PALB2 has emerged as a relevant cancer susceptibility gene and assessment of PALB2 variants is informative in genetic counseling of patients at high risk of developing cancer." (PMID 28858227, 2017). "In the present study, we provide additional evidence that impaired PALB2 chromatin association may be linked with cancer development." (PMID 29387807, 2017). "Within this region, three cancer-associated mutations affecting two amino acids, namely Gly25 (changed to Arg, G25R) and Trp31 (changed to Cys or Arg, W31C and W31R, respectively) were found to disrupt the interaction with PALB2." (PMID 27490902, 2016). "In 2009, PALB2 was reported as the first candidate cancer predisposition gene discovered by MPS." (PMID 27279102, 2016). "Indeed few studies of PALB2 mutations have analysed significant numbers of family cancer clinic-ascertained cases or matched controls." (PMID 26283626, 2015). "PALB2 is comprised of 13 exons spanning a 38 kb region on chromosome 16p12.1 and mutation screening is complicated by the diversity of variants (including missense mutations) identified in cancer cases." (PMID 23302520, 2013). "Indeed during the preparation of this manuscript another PALB2 carrier harboring the p.Q775X variant was identified in the Hereditary Cancer Clinics affiliated with McGill University Health Centre." (PMID 23302520, 2013). "Thus, in these patients with clear familial history of cancer, the evaluation of mutations in other genes, like PALB2, CHEK2 and RAD51C, should also be considered." (PMID 22655046, 2012). "To date, PALB2 alterations have been associated with familial breast and pancreatic cancers." (PMID 20122277, 2010). "It is unclear how the PALB2 deficiency contributes to cancer development." (PMID 20122277, 2010). "Interestingly, the presence of these two alterations in carcinomas appears to be more frequent than just one occurring by chance, considering the low frequency of PALB2 and BRCA2 mutations in control populations." (PMID 20122277, 2010). "“Cancer” and related categories such as “Cell death and survival”, “Cellular movement”, “Cellular growth and proliferation”, as well as “Cell-to-cell signaling and interactions” were among the top altered functions identified in both bi- and monoallelically PALB2-deficient cell lines." (PMID 38597967, 2024). "Notably, the p.L24F and p.L35F variants not only reduced HR activity of PALB2 but also abrogated G2/M checkpoint maintenance, which may exacerbate genomic instability and lead to cancer susceptibility." (PMID 35853885, 2022). "Interestingly, database (ClinVar/MedGen) and literature reports suggest that human individuals with a hereditary predisposition for BRCA1/2- and PALB2-associated cancers carry germline point mutations of predominantly hydrophobic residues in the human RAD50 beta-sheet motif." (PMID 35501303, 2022).
cancer (continued). "With results from such studies in mind, findings from functional assays that show which VUS are damaging or functional, may prove to be valuable for predicting platinum- and/or PARPi-based therapy response in cancer patients that carry PALB2 variants that abrogate HR." (PMID 33195396, 2020). "Pathogenic PALB2 mutations have also been identified in patients with other cancers, such as gastric and prostate cancer; however, whether these mutations confer an increased cancer risk for these cancer types requires further research." (PMID 32185139, 2020). "Therefore, evaluating PALB2 VUS impact in cancer predisposition is central for risk assessment." (PMID 28858227, 2017). "The contribution of PALB2 pathogenic variants is already recognized in clinical oncology; a large number of truncating variants have been reported to be associated with different forms of cancer, but a significant number of missense variants remain unclassified." (PMID 28858227, 2017). "Several studies have suggested that PALB2-deficient cancers could be sensitive to PARP inhibitors." (PMID 28027327, 2016). "In contrast, data on cancer risk for PALB2, RAD51C, and RAD51D GPV carriers are limited and lifetime cancer risks largely depend on both family history and personal risk factors, such as age of menarche, use of oral contraceptives, and the number of children." (PMID 40428378, 2025). "A retrospective case–control study used data on 150,962 women tested with a multigene hereditary cancer panel to evaluate an 86-SNV PRS in BRCA1, BRCA2, CHEK2, ATM, and PALB2 P/LP variant carriers." (PMID 39858629, 2025). "We successfully identify cancer-associated genes such as BRCA1, BRCA2, PALB2, and TCEAL4, all exhibiting the sought-after expression patterns." (PMID 40983914, 2025). "Approximately 11% to 17% of patients with metastatic PCa have been reported to have germline mutations in key hereditary cancer genes, including BRCA2, ATM, CHEK2, BRCA1, RAD51D, or PALB2, which represents a substantial population burden." (PMID 41086012, 2025). "Some other genes, like CHEK2, ATM, PALB2, and BRIP1, show a modest tendency for BC; however, patients with these genes' mutations have 2–3 times the high risk of developing a malignant tumor." (PMID 40755497, 2025). "Of these, 103 patients (8.6% of the total sample) carried germline pathogenic variants in genes that have been definitively linked to an increased risk of PC or other types of cancers (BRCA2, ATM, CHEK2, NBN, BRCA1, PALB2, BRIP1 and BARD1)." (PMID 41465280, 2025). "Approximately 10% of patients with aggressive PC carry germline pathogenic variants in genes with established roles in cancer predisposition (BRCA2, ATM, CHEK2, NBN, BRCA1, PALB2, BRIP1, BARD1)." (PMID 41465280, 2025). "In other solid tumors, BRCA1/2, PALB2, or RAD51-mutated cancers have demonstrated sensitivity to platinum-based chemotherapy and PARP inhibition, supporting the rationale for evaluating similar approaches in pNENs." (PMID 41294693, 2025).